SLC38A1 (solute carrier family 38 member 1)
Description:
Symporter that cotransports short-chain neutral amino acids and sodium ions from the extracellular to the intracellular side of the cell membrane. The transport is elctrogenic, pH dependent and driven by the Na(+) electrochemical gradient. Participates in the astroglia-derived glutamine transport into GABAergic interneurons for neurotransmitter GABA de novo synthesis (By similarity). May also contributes to amino acid transport in placental trophoblasts. Also regulates synaptic plasticity.
Synonyms: ATA1; NAT2; SAT1; SNAT1
Tractability: Antibody: UniProt places it where antibodies can reach, with high confidence; its Gene Ontology location is reachable by antibodies, with high confidence; UniProt predicts a signal peptide or a membrane-spanning region. PROTAC: ubiquitination databases record sites on it; its protein half-life has been measured.
Gene: Protein-coding gene on chromosome 12 (46,183,054 to 46,270,070, reverse strand). Ensembl gene ENSG00000111371.
Subcellular location: Cell membrane
Pathways (Reactome):
Neuronal System: Astrocytic Glutamate-Glutamine Uptake And Metabolism
Transport of small molecules: Amino acid transport across the plasma membrane
Gene Ontology:
Molecular function: protein binding; alanine:sodium symporter activity; amino acid transmembrane transporter activity; amino acid:sodium symporter activity; glycine:sodium symporter activity; L-amino acid transmembrane transporter activity; L-asparagine:sodium symporter activity; L-glutamine transmembrane transporter activity; neutral L-amino acid transmembrane transporter activity; neutral L-amino acid:sodium symporter activity; proline:sodium symporter activity
Biological process: amino acid import; amino acid transmembrane transport; amino acid transport; glutamine transport; L-alpha-amino acid transmembrane transport; L-glutamine import across plasma membrane; neurotransmitter uptake; neutral amino acid transport; regulation of synaptic plasticity; regulation of synaptic transmission, GABAergic; transport across blood-brain barrier; alanine transport; asparagine transport; female pregnancy; glycine transport; sodium ion transmembrane transport
Cellular component: extracellular exosome; plasma membrane; basolateral plasma membrane; external side of apical plasma membrane; membrane; neuronal cell body; axon
Genetic constraint (gnomAD): Loss-of-function variants: 8 observed, 27.87 expected, observed/expected ratio (o/e) 0.29, 90% interval 0.17 to 0.52. The upper end of that interval is the gene's LOEUF score, 0.52, which puts it in group 2 of 6, group 1 being the genes least tolerant of losing a copy. Missense variants: 325 observed, 451.73 expected, observed/expected ratio (o/e) 0.72, 90% interval 0.66 to 0.79. Synonymous variants: 146 observed, 161.82 expected, observed/expected ratio (o/e) 0.9, 90% interval 0.79 to 1.03.
Homologues: Orthologues: dog SLC38A1 (97% identical), pig SLC38A1 (96% identical), chimpanzee SLC38A1 (95% identical), macaque SLC38A1 (94% identical), rat Slc38a1 (94% identical), guinea pig SLC38A1 (93% identical), mouse Slc38a1 (93% identical), rabbit SLC38A1 (89% identical), tropical clawed frog slc38a1 (74% identical), Drosophila melanogaster CG32079 (18% identical), Drosophila melanogaster CG13384 (16% identical), Caenorhabditis elegans slc-36.3 (16% identical), and 14 more. Paralogues in human: SLC38A4 (53% identical), SLC38A2 (51% identical), SLC38A3 (49% identical), SLC38A5 (45% identical), SLC38A6 (38% identical), SLC38A11 (23% identical), SLC38A7 (22% identical), SLC38A10 (20% identical), SLC36A1 (20% identical), SLC36A2 (20% identical), SLC36A4 (19% identical), SLC38A8 (18% identical), and 3 more.
Diseases named in the same sentence as SLC38A1 in open-access papers:
SLC38A1 is named in the same sentence as 79 diseases in open-access papers, as found by Europe PMC text mining. Sharing a sentence is not in itself a finding about the gene and the disease. The quoted sentences say what the papers report.
hepatocellular carcinoma (15 papers, 2013 to 2025). A malignant tumor that arises from hepatocytes. "Pervious study has showed that SLC38A1 was highly expressed in hepatocellular carcinoma tissues, and associated with a poor prognosis." (PMID 38635778, 2024). "In hepatocellular carcinoma (HCC), SLC38A1 is significantly overexpressed and associated with poor overall survival and recurrence-free survival." (PMID 40315269, 2025). "Similar to other human malignancies such as gastric cancer, hepatocellular carcinoma and malignant melanoma, SLC38A1 mRNA expression was found to be upregulated in OSCC/HNSCC compared to the normal control tissues in the external transcriptomic datasets." (PMID 38254895, 2024). "Consistent with these abilities, increased expression of SLC38A1 has been reported in several human malignancies such as gastric cancer, hepatocellular carcinoma and malignant melanoma as compared to the respective normal control tissues, indicating a link between SLC38A1 and human malignancies." (PMID 38254895, 2024). "However, the correlation between SLC38A1 expression, prognosis, and immune infiltration in hepatocellular carcinoma (HCC) has yet to be elucidated." (PMID 34697542, 2021). "In hepatocellular carcinoma, previous study proved that YAP1/TAZ activated the mTORC1 pathway via up- regulating amino acid transporters (SLC38A1 and SLC7A5) to promote cell growth." (PMID 32003757, 2020). "created a novel Hepatocellular Carcinoma prediction model that integrates 7 GlnMgs, including SLC1A5, GAPDH, SLC38A1, SLC38A7, FTCD, MTHFS, and GOT2 might be utilized to predict prognosis in HCC." (PMID 37377916, 2023).
breast carcinoma (14 papers, 2013 to 2025). "For instance, trastuzumab-resistant HER2-positive breast cancer was found associated with downregulated TGFBI, CXCL2, and SLC38A1, which was silenced by DNA hypermethylation." (PMID 40464376, 2025). "This analysis showed that SLC38A1 is upregulated in estrogen receptor-positive luminal-type breast cancer." (PMID 38539825, 2024). "SLC38A1 is highly expressed in breast cancer, HCC, gastric cancer, and colorectal cancer and is associated with proliferation, metastasis, invasion, cell death, and poor prognosis." (PMID 38658981, 2024). "The expression of Slc38a1 is slightly increased in PyMT-driven breast cancer than in Neu- and HRAS-driven breast cancers." (PMID 34704597, 2021). "Slc38a1 and Slc38a2 are expressed at low levels in normal mammary tissue, and their expression is up-regulated in all three subclasses of breast cancer." (PMID 34704597, 2021). "Slc1a5 shows an expression pattern similar to that of Slc38a1; it is expressed at low levels in normal mammary tissue and it is up-regulated in all three subclasses of breast cancer." (PMID 34704597, 2021). "Serine is a small, neutral amino acid and can be imported into the cell by Na+-dependent transporters like ASCT1 (SLC1A4), which is upregulated in both breast cancer and lung cancer, system A transporters like SNAT1 (SLC38A1), and the ASC system." (PMID 33511116, 2020). "Hypoxia induced HIF1α positively regulates SLC38A1 and SLC38A2 expression in adipose cells during obesity and in breast cancer cells, respectively." (PMID 36613847, 2022). "SLC38A1, also known as sodium-coupled neutral amino acid transporter 1 (SNAT1), is upregulated in both breast cancer cell lines (two originated from human (MCF-7, MDA-MB-231) and one from mouse (4T1)) and human breast cancer tissues." (PMID 29562706, 2018). "Because SLC38A1 overexpression is correlated with increased phosphorylation of AKT, crosstalk between SLC38A1 and AKT signaling may affect breast cancer progression." (PMID 29562706, 2018).
gastric cancer (10 papers, 2014 to 2024). A primary or metastatic malignant neoplasm involving the stomach. "More pronounced SLC38A1 expression in gastric cancer tissues was significantly associated with age, differentiation status, lymph node metastasis, TNM stage and PCNA (proliferating cell nuclear antigen) expression." (PMID 24712400, 2014). "Therefore, we supposed that overexpression of SLC38A1 is a significant factor associated with a poor prognosis, and might be a marker to forecast gastric cancer patients’ recurrence and survival." (PMID 24712400, 2014). "Meanwhile, the high expression of SLC38A1 is closely related to the occurrence, recurrence, and metastasis of solid tumors such as gastric cancer, colon cancer, and cervical cancer, indicating poor prognosis." (PMID 32751923, 2020). "The high expression of SLC38A1 was detected in gastric cancer, and was related with tumor differentiation degree, TNM staging, lymph node metastasis, and prognosis." (PMID 30349810, 2018). "Our previous studies, using gene chip analysis, suggested elevated SLC38A1 mRNA expression in gastric cancer (unpublished data)." (PMID 24712400, 2014). "Immunohistochemical staining was used to analyze the expression of SLC38A1 in gastric cancer tissues and adjacent healthy mucosa in 896 patients with pathologically confirmed gastric cancer who had underwent R0 resection." (PMID 24712400, 2014). "In contrast, strong staining of SLC38A1 protein was found in the cytoplasm in 495 out of the 896 gastric cancer samples." (PMID 24712400, 2014). "SLC38A1 is overexpressed in gastric cancer, which suggests that it is contributory to tumor progression." (PMID 24712400, 2014). "Potential correlation of SLC38A1 with the prognosis was examined using a multivariate analysis, and the biological role of SLC38A1 in proliferation and progression was examined in cultured gastric cancer cells using siRNA." (PMID 24712400, 2014). "In the current study, we compared the expression of SLC38A1 in gastric carcinoma in contrast with healthy adjacent gastric mucosa at the protein level." (PMID 24712400, 2014). "SLC38A1 has been proved to be a potential oncogene in colorectal cancer and gastric cancer." (PMID 34291083, 2021). "Similarly, other studies have indicated that high levels of SLC38A1 expression represented an unfavorable prognostic indicator for human osteosarcoma, cholangiocarcinoma, gastric cancer, and acute myeloid leukemia." (PMID 34697542, 2021). "SH-10-TC cells (a gastric cancer cell line) were used to examine whether silencing SLC38A1 with siRNA could affect cell viability, migration and invasion." (PMID 24712400, 2014). "The results from the experiments using cultured gastric cancer cells indicated that SLC38A1 expression could be used as an indicator of disease aggressiveness." (PMID 24712400, 2014). "In conclusion, our study showed that SLC38A1 expression was closely associated with age, differentiation status, lymph node metastasis, TNM stage and PCNA expression, as well as a worse prognosis in patients with gastric cancer." (PMID 24712400, 2014). "An elevated expression of SLC38A1 has been found to be closely linked to differentiation status, lymph node metastasis and TNM staging, and is thus implicated in the growth, invasion, metastasis and progression of gastric carcinomas." (PMID 24712400, 2014). "Consistent with the physiological and pathological roles of glutamate in cancer development, we found marked differences in the expression of SLC38A1 in gastric cancer relative to adjacent non-cancerous tissue." (PMID 24712400, 2014). "In the present study, we found an increased expression of SLC38A1 in gastric carcinomas, relative to adjacent non-cancerous gastric mucosa, suggesting that SLC38A1 might play an important part in gastric cancer malignant transformation." (PMID 24712400, 2014).
osteosarcoma (10 papers, 2017 to 2023). A usually aggressive malignant bone-forming mesenchymal neoplasm, predominantly affecting adolescents and young adults. "SLC38A1/SNAT1 has been found to play an essential role in human development, but its role in osteosarcoma (OS) has yet to be evaluated." (PMID 29108276, 2017). "As proof, ASCT2 (SLC1A5) knockdown in osteosarcoma and cervical cancer cells can induce upregulation of SNAT1 (SLC38A1)." (PMID 33511116, 2020). "Other glutamine transporters such as SNAT1 (SLC38A1) and SNAT2 (SLC38A2) have also been shown to play a role in glutamine uptake in triple-negative breast cancer, and in osteosarcoma and cervical cancer cells." (PMID 29940911, 2018). "However, in some tumor cell lines, such as 143B osteosarcoma cells, loss of SLC1A5 did not suppress tumor growth, but instead elicit an amino acid starvation response and up-regulation of SLC38A1, indicating that SLC38A1 may act as a rescue transporter when SLC1A5 is blocked." (PMID 36262284, 2022).
melanoma (8 papers, 2022 to 2026). A malignant, usually aggressive tumor composed of atypical, neoplastic melanocytes. "In the same line, Böhme-Schäfer and coauthors have reported that SLC38A1 expression is associated with primary and metastatic cell lines and increased proliferation, colony formation, migration and invasion abilities of malignant melanoma cells." (PMID 38254895, 2024). "The expression of circTADA2A is significantly downregulated in melanoma cell lines and is positively associated with melanoma progression by interacting with CCHC-type zinc finger nucleic acid binding protein (CNBP) to influence the expression of solute carrier family 38 member 1 (SLC38A1)." (PMID 38635778, 2024). "CircTADA2A suppresses melanoma progression by regulating CNBP/SLC38A1 axis, indicating a potential therapeutic target in melanoma." (PMID 38635778, 2024). "Taken together, these results showed that circTADA2A suppressed melanoma cell progression via repressing CNBP/ SLC38A1 pathway." (PMID 38635778, 2024). "Mechanistically, circTADA2A interacted with CNBP, acting to suppress the binding of CNBP to the SLC38A1 promoter and subsequently restrained SLC38A1 transcription, which resulting in repression of melanoma progression." (PMID 38635778, 2024). "In order to further investigate the interplay effects between circTADA2A and CNBP in regulating SLC38A1 expression and melanoma progression, A375 and A2058 cells were co-transfected with circTADA2A overexpression vector, CNBP overexpression vector and SLC38A1 knockdown vector." (PMID 38635778, 2024). "Moreover, stable overexpression of circTADA2A attenuated the protein expression levels of SLC38A1 in melanoma cells, which were blocked by CNBP overexpression." (PMID 38635778, 2024). "Knockdown SLC38A1 expression reduce the proliferation rate of melanoma cells." (PMID 38635778, 2024). "In this study, we observed that the Gln transporter SLC38A1/SNAT1 is highly expressed in human melanoma tissue, as well as many melanoma cell lines and investigated the functional role of SNAT1 in cell proliferation, migration, invasion, and senescence induction in melanoma." (PMID 35565278, 2022). "Importantly, the expression of SLC38A1 is significantly up-regulated in human melanoma tissue." (PMID 38635778, 2024). "CircTADA2A inhibited melanoma growth and metastasis by interacting with CNBP protein to modulate gene transcription of SLC38A1." (PMID 38635778, 2024). "Furthermore, l‐gamma‐glutamyl‐p‐nitroanilide, an inhibitor of the SLC1A5 (ASCT2) and SLC38A1 (SNAT1) transporters, decreased lipid peroxide levels and rescued erastin‐induced ferroptosis in melanoma cells." (PMID 40703196, 2025). "To emphasize the importance of glutamine transporters in melanoma, we investigated the gene expression of glutamine transporters SLC38A1/SNAT1, SLC38A2/SNAT2, SLC1A5/ASCT2, and SLC7A5/LAT1, which showed expression in RNA sequencing analysis in several melanoma cell lines." (PMID 35565278, 2022). "As MeAIB does not just selectively inhibit SNAT1/SLC38A1, but also SNAT2/SLC38A2 and SNAT4/SLC38A4, we further analyzed specific SNAT1 effects using an siPool for selective downregulation of SNAT1 mRNA in melanoma cells." (PMID 35565278, 2022).
glioma (7 papers, 2014 to 2025). A benign or malignant brain and spinal cord tumor that arises from glial cells (astrocytes, oligodendrocytes, ependymal cells). "In our previous in vitro culture studies using rat cortical astrocytes and astrocytic C6 glioma cells, artificial overexpression of Slc38a1 invariably led to exacerbated vulnerability to oxidative stress by hydrogen peroxide." (PMID 31952134, 2020). "These included activator protein-1 (AP1) and cyclic AMP responsive element-binding protein (CREB), which were both shown to be able to stimulate the promoter activity of the Slc38a1 gene in C6 glioma cells." (PMID 31952134, 2020). "Enhanced SLC38A1 expression has been observed in several other types of malignancies, including liver cancer, Hilar cholangiocarcinoma and C6 glioma." (PMID 24712400, 2014). "In a current ongoing unpublished research, our preliminary findings show that the glutamine transporter sodium-coupled neutral amino-acid transporter (SNAT) 1 (Slc38a1) is involved in 18F-DOPA uptake of cell lines of pediatric high-grade gliomas, in addition to LAT1." (PMID 33204317, 2020). "The expression of SLC38A1, another glutamine transporter on the cell membrane, was less different in these cell lines, suggesting SLC1A5 was the main glutamine transporter in glioma cells." (PMID 36566214, 2022).
lung carcinoma (7 papers, 2016 to 2025). "SLC1A5 and SLC38A1 are two critical Gln importers and play critical roles in regulating ferroptosis and lung cancer." (PMID 36654781, 2023). "It regulates lung cancer cell proliferation and ferroptosis mainly by inhibiting miR-299-3p and enhancing solute carrier family 38 member 1 (SLC38A1) expression." (PMID 37005430, 2023). "OGFRP1 regulates lung cancer cell proliferation and ferroptosis by inhibiting miR-299-3p to enhance SLC38A1 expression." (PMID 36685932, 2022). "However, some transporters, like SLC38A1, a transporter found by us to be up-regulated in lung cancer, transport Na+ along with glutamine, which drives the glutamine transport." (PMID 27294516, 2016). "The miR-299-3p/SLC38A1 axis has revealed OGFRP1 as a key regulator of cellular proliferation and ferroptosis in lung cancer." (PMID 40078365, 2025). "MiR-338-3p targeting SLC1A5 in retinal pigment epithelium cells and miR-299-3p targeting SLC38A1 in lung cancer cells reduce glutamine absorption and GSH levels to promote ferroptosis, whereas lncOGFRP1 attenuates ferroptosis by blocking miR-299-3p in lung cancer cells." (PMID 37686142, 2023).
cervical cancer (5 papers, 2018 to 2026). A primary or metastatic malignant neoplasm involving the cervix. "In cervical cancer, it was found that METTL3 increased the metabolism of glutamine in cervical cancer cells through m6A methylation of SLC38A1 mRNA157." (PMID 41522342, 2026).
pulmonary fibrosis (4 papers, 2022 to 2024). Chronic progressive interstitial lung disorder characterized by the replacement of the lung tissue by connective tissue, leading to progressive dyspnea, respiratory failure, or right heart failure. "ZFAS1 facilitates the transition of lung fibroblasts to myofibroblasts and ferroptosis by serving as a ceRNA via the miR-150-5p/SLC38A1 axis in the course of pulmonary fibrosis." (PMID 39296014, 2024). "lncRNA ZFAS1 acts as a competitive endogenous RNA (ceRNA) and sponge miR-150-5p to downregulate the expression of SLC38A1 to attenuate iron death and the progression of pulmonary fibrosis." (PMID 36187333, 2022). "In bleomycin (BLM)-induced pulmonary fibrosis rat lung tissues and transforming growth factor-β1-treated HFL1 cell models, downregulation of miR-150-5p targets SLC38A1 expression, leading to increased expression of inflammatory cytokines, fibroblast activation, and elevated ROS levels." (PMID 39834787, 2024).
acute myeloid leukemia (3 papers, 2021 to 2024). Acute myeloid leukemia (AML) is a group of neoplasms arising from precursor cells committed to the myeloid cell-line differentiation. "Dysregulation of SLC38 transporters may contribute to tumor initiation and progression, with high SLC38A1 expression linked to poorer prognosis in acute myeloid leukemia (AML) and shorter overall survival." (PMID 38534987, 2024).